MAF (MAF bZIP transcription factor)
Diseases named in the same sentence as MAF in open-access papers (continued):
Sharing a sentence is not in itself a finding about the gene and the disease.
tumor (71 papers, 2008 to 2025). "For example, MST1 is essential for the expression of MAF which has a role in cell death, inflammatory responses of tumor-associated macrophages, and macrophage differentiation (44, –, 46, 60)." (PMID 38624208, 2024). "A recent report demonstrated that c-MAF contributes to the tumor-associated macrophages (TAMs) dampening T-cell effector function during lung cancer." (PMID 35359922, 2022). "Furthermore, MAF loss or mislocalization in FFPE LSCC tumor samples might suggest that MAF acts as a LSCC tumor suppressor by regulating apoptosis." (PMID 34356658, 2021). "We propose that MAF overexpression supports BCa progression beyond proliferation and primary tumour growth, possibly by directly activating the bone microenvironment to a more metastasis-receptive state." (PMID 37945904, 2023). "In fact, murine Maf downregulation results in enhanced antitumor immunity, and human MAF has been detected in tumor-infiltrating macrophages/monocytes and circulating monocytes from non-small cell lung carcinoma (NSCLC) patients." (PMID 36380627, 2023). "AP-1 is a dimeric complex that includes the JUN, FOS, ATF and MAF proteins that form diverse homodimers and heterodimers in regulating oncogenic and tumor-suppressive activities." (PMID 35022313, 2022). "MAF is an interesting novel tumor suppressor candidate that belongs to a transcription factor family comprising seven proteins." (PMID 34356658, 2021). "It is known that M2-TAMs are the main tumor-associated anti-inflammatory macrophages with relatively high expression of CD163, MRC1, MS4A4, and MAF." (PMID 33303760, 2020). "c‐MAF expression is induced by TGFβ and a recent patent application showed that DOCK4 expression correlates with MAF expression within primary tumours." (PMID 30426503, 2019). "Less clear is the role of MAF having been described either as an oncogene or as a tumor suppressor, depending on the cell context." (PMID 29755661, 2018). "By contrast, up-regulation of c-MYC, MAFG, and c-MAF or attenuation of MATa1 expression by knock-down triggered increased tumor cell growth and invasion in vivo." (PMID 28422055, 2017). "Remarkably, MAT1A overexpression, or c-MYC, MAFG, or c-MAF inhibition in tumor cells dramatically inhibited their in vitro and in vivo growth." (PMID 28422055, 2017). "To search for potential MAF loss and to analyze its cellular distribution in LSCC, we evaluated MAF protein expression in 128 formalin-fixed, paraffin-embedded tumor samples from LSCC patients, as well as expression in the control group that consisted of 19 normal mucosa cases." (PMID 34356658, 2021). "MAF is a transcription factor that may act either as a tumor suppressor or as an oncogene, depending on cell type." (PMID 34356658, 2021). "MAF amplification (at 16q23) leads to overexpression of MAF (mesenchymal aponeurotic fibrosarcoma gene, an AP-1 family transcription factor) in the primary tumor." (PMID 34377934, 2021). "Based on these results, we also suggest that MAF may show a suppressive role in this tumor via regulation of apoptosis." (PMID 34356658, 2021). "These MØs express CD163 and M2-specific markers (increased expression of FOLR2 and MAF and reduced expression of ActA), and show an upregulated expression of different factors that favour tumour progression (including, among others, IL-10, TGF-β, IL-6, IL-8, IDO1, COX2 and GAL-1)." (PMID 31337120, 2019). "In addition, in the M2a state, MAF bZIP transcription factor B (MAFB) and heat shock transcription factor 1 (HSF1) TFs, whose elevated expression in TAMs associates with more aggressive tumor growth, had significantly upregulated phosphosites." (PMID 41255709, 2025). "In addition, MAF antagonizes Ras-driven tumor cell proliferation." (PMID 37779141, 2023). "Importantly, we demonstrate that MAF amplification and overexpression in ER+ tumours reprogram the canonical cistrome to include previously unknown enhancer and transcriptional activity, thereby enhancing metastasis to bone." (PMID 37945904, 2023).
tumor (continued). "In HCC, all-trans retinoic acid (ATRA) enhances TFPI2 via retinoic acid receptor alpha (RARα), modulated by MAF bZIP transcription factor B (MAFB, activator) and MAFF (repressor), influencing tumor invasion." (PMID 40361374, 2025). "An orthotopic B.C. transplanted tumor model in mice with humanized immune systems was constructed, in which the Role of CHI3L1/MAF/CTLA4 in the immune escape of TNBC was explored." (PMID 37838657, 2023). "And lastly, CD8+ T cells in the tumor periphery exhibited a transcription factor profile of exhausted T cells with high expression of NR4A1, MAF, and IRF4, which were implicated in T cell dysfunction and exhaustion." (PMID 38127790, 2023). "In our previous study, we demonstrated that MAF is downregulated at the mRNA level in LSCC cell lines and tumor samples, and we identified the putatively oncogenic miR-1290 to be a regulator of the level of MAF protein in the analyzed LSCC cell lines." (PMID 34356658, 2021). "Double-staining immunohistochemistry of CD163/p-STAT, CD68/pSTAT1, CD163/c-MAF, and CD68/c-MAF was performed on tumor samples taken at the time of diagnosis." (PMID 26335330, 2015). "M2‐TAMs are tumor‐promoting macrophages and showed high expression of MRC1, CD163, MARCO, and MAF." (PMID 36529697, 2023). "As much as 58% of analyzed LSCC cases showed either complete absence of MAF or lack of nuclear MAF expression, while 100% of non-tumor tissue revealed nuclear MAF expression through immunohistochemistry." (PMID 34356658, 2021). "Thus, we propose that when FOXI3 in tumor cells modulate the secretion of other bone factors including SPOCK1, Dlx, MAF, PthrP, HAS2, SVEP1, TGFβ3, and FGF which further primes the microenvironment, creates a crosstalk to help tumors grow in the bone." (PMID 30018953, 2018). "Our results were consistent with those of the meta-analysis such that GSN, SPTBN1, SFRP1 and MAF were down-regulated in most tumor samples with respect to their matched non-tumor samples whereas COX6C, RAD21, GSPT1, NME1 and PTTG1 were up-regulated." (PMID 19116033, 2008). "As the dysregulation of immunoproteasomes and chemokines promotes immune evasion of cancer cells, suppression of MAF, GATA6, and DAB2 may contribute to the maintenance of the tumor microenvironment, which is advantageous for EMT and immune escape in the early stages of tumorigenesis." (PMID 37779141, 2023). "Moreover, by combining mRNA expression microarray data for the group of LSCC cell lines and no-tumor controls with public available miRNA target databases we indicated potential miR-1290 target genes downregulated in LSCC namely MAF and ITPR2." (PMID 26694163, 2015). "Therefore, the antitumoral effects of MTX might not be limited to its antiproliferative action on tumor cells but may also result from its ability to “reeducate” macrophages, an effect dependent on the GSK3β-MAF axis." (PMID 36380627, 2023). "To verify if the observed downregulation of MAF, ITPR2 and RGS5 was characteristic also for primary LSCC specimens, we analyzed group of 22 tumors and five no tumor controls by quantitative real time PCR." (PMID 26694163, 2015). "Although the autophagy-related genes (ARGs) identified in our study did not directly overlap with classical MM driver genes such as MAF translocations, certain metabolic regulators like ATIC may indirectly assist tumor cells in adapting to the bone marrow microenvironment." (PMID 41040512, 2025).
cancer (48 papers, 2010 to 2025). A tumor composed of atypical neoplastic, often pleomorphic cells that invade other tissues. "We observed similar cancer-specific H3K4me3-BDs associated with hijacking of super-enhancers of other common oncogenes in B cell (MAF, MYC, and FGFR3/NSD2) and T cell malignancies (LMO2, TLX3, and TAL1)." (PMID 34933939, 2022). "In an attempt to explain this observation, we excluded such cancer-related mechanisms as loss-of-function mutations or promoter DNA hypermethylation as being responsible for the downregulation of MAF in LSCC." (PMID 34356658, 2021). "These interacting regions were enriched with binding motifs for forkhead box (FOXH1, FOXQ, FOXJ3, FOXO4), zinc finger (ZNF214, ZNF134, ZNF549 and ZNF563) and musculoaponeurotic fibrosarcoma proteins (MAFK, MAFB, MAFG, MAFF and MAF), which have all been implicated in cancer metastasis." (PMID 40099944, 2025). "We next focused on high-confidence MAF interactors that could be connected to the MAF-mediated global chromatin opening via histone methylation and that have previously been linked to cancer." (PMID 37945904, 2023). "Consistent with MAF as a critical controller for immunosuppressive macrophage polarization and function in cancer, MAF was found as a transcription factor regulon upregulated during macrophage differentiation." (PMID 38408082, 2024). "Studies have shown that Gc-MAF is an advanced and promising immunotherapy for the treatment of cancer." (PMID 37900279, 2023). "We also found copy number loss of cancer genes such as CCNE1, MAF, MAFB, MYC, ZNF479, and MGMT and copy number gain of FOXA2, CDH10, and GPC5 in at least two WDPM cases." (PMID 32545767, 2020). "Predicted mRNA targets of the miRNAs significantly regulated after ATM depletion included many genes associated with cancer formation and progression, such as SOCS1 and the proto-oncogene MAF." (PMID 23741392, 2013). "Therefore, the downregulation of MAF, GATA6, and DAB2 may be associated with dysregulated proteasomal function, resulting in EMT and the immune escape of cancer cells." (PMID 37779141, 2023). "And USP5 could regulate the stability of many tumorigenesis‐associated proteins, such as forkhead box M1 (FoxM1), MAF bZIP transcription factor (c‐Maf), Tu translation elongation factor, mitochondrial, and snail family transcriptional repressor 2 (SNAI2) to promote the cancer progression." (PMID 37492786, 2023). "Most of the NRF2 pathway-related genes showed extensively negative relationships with RNAss; for example, the expressions of FOS, JUN, MAF, MAFK, and PRRT2 in various cancers were negatively related to RNAss." (PMID 35242279, 2022). "In ESCC cell lines, we examined all AP-1 transcription factors including JUN, FOS, MAF, and ATF family members and found that FOSL1, MAFK, BATF, and ATF5 are upregulated compared to non-cancer cells." (PMID 34722266, 2021). "Comparative analysis of methylation sites associated with genes within the KEAP-NRF2 and PI3K pathway in this study suggested the MAF transcription factor and NFE2L2 (NRF2) are hypermethylated in the four TCGA cancers screened." (PMID 33143142, 2020). "This identified ATF4, FOXO1, HIF1A, MAF, MYC, and SREBP1 in FGFR-dependent cancer cells whereas ATF4 and MYC in EGFR-addicted cancer cells, which were required for the transcription of the signature genes in glycolysis or SSP." (PMID 31221965, 2019). "The involvement of MAF and ITPR2 in the regulation of apoptosis and radioresistance reflects therefore well the role of miR-1290 reported in other cancers." (PMID 26694163, 2015). "For the prostate dataset, our results show that three genes, namely MAF, ABL1 and SERPINB5, are cancer ones and most other top-ranked genes have a direct interaction with known cancer genes." (PMID 22830977, 2012).
cancer (continued). "It has been reported that TFs mediate the functions of lncRNAs in several essential biological processes, such as the lnc-ISIR/IRF3 axis in autoinflammation, the lnc-MAF/MAFB axis in epidermal differentiation, and the lnc-ANRASSF1/PRC2 axis in cancer cell proliferation." (PMID 37107173, 2023). "For example, increased expression of oncogenic transcription factors such as MAF and CEBPA indicate miRNAs may regulate large networks of genes involved in cancer formation." (PMID 23741392, 2013). "However, in LSCC, 74/128 (58%) cases demonstrated aberrant expression of MAF, where in 8/74, MAF was entirely absent in cancer cells, and in 66/74, only cytoplasmatic expression was observed." (PMID 34356658, 2021). "Moreover, MAF played a role in promoting bone metastasis rather than cancer cell proliferation in vivo, which was consistent with our scientific hypothesis." (PMID 33585235, 2020).
infection (18 papers, 2009 to 2025). The state of being infected such as from the introduction of a foreign agent such as serum, vaccine, antigenic substance or organism. "Ranked regulon activity analysis of key TFs during early infection further confirmed the predominant contributions of BATF3, MAF, and CREB3 within AntiviralMac and SusceptibleMac populations." (PMID 40723441, 2025). "Although the up-regulation of c-MAF was suppressed in bovine monocytes during early infection, the c-MAF levels were still much higher than those observed in established T. annulata-infected cell-lines." (PMID 19303416, 2009). "In contrast, during early infection T. annulata inhibited the up-regulation of c-MAF transcription induced by in vitro differentiation of monocytes to mφ by 80%." (PMID 19303416, 2009). "Transcriptome profiling of bovine monocytes following infection with T. annulata revealed that c-MAF was one of the most differentially regulated genes." (PMID 19303416, 2009). "Many LCM-associated regulons were not altered by infection (C/EBPβ), while others were lost (RARG and MAF) and others gained (KLF4, STAT3, FOSB, and BHLHE40)." (PMID 36948193, 2023). "A second Ankara strain cell-line was generated on a separate occasion from infection of purified monocytes from the same animal and buparvaquone treatment also failed to modulate c-MAF mRNA levels in this cell-line (data not shown)." (PMID 19303416, 2009). "We have previously reported that a lack of MALAT1 results in lower levels of MAF and IL10 in mice and as a consequence, greater host resistance to infection or increased immunopathology." (PMID 36869729, 2023).
inflammation (1 paper, 2019). Aberrant reaction of the microcirculation characterized by movement of fluid and leukocytes from the blood into extravascular tissues. "Here we demonstrate that the transcription factor MAF plays a central role in T cells for the prevention of gastro-intestinal inflammation." (PMID 30992496, 2019).
MAF also shares sentences with these, for which no sentence is quoted: multiple myeloma (27 papers); malaria (6); Crohn disease (4); endometriosis (3); immune diseases (3); inflammatory bowel disease (3); schizophrenia (3); T-cell lymphomas (3); Type 1 diabetes (3); type 2 diabetes (3); allergic rhinitis (2); cervical cancer (2); deafness (2); hepatocellular carcinoma (2); Hyperglycemia (2); Insulin resistance (2); Intellectual disability (2); leukemia (2); Nephropathy (2); rheumatoid arthritis (2); acute myeloid leukemia (1); Allergy (1); Alzheimer disease (1); anemia (1); Anophthalmia (1); aphakia (1); B cell lymphoma (1); bipolar disorder (1); chronic myeloid leukemia (1); Cognitive impairment (1).
A further 43 diseases each share a sentence with MAF in 1 paper.